LTA (lymphotoxin alpha)
Diseases named in the same sentence as LTA in open-access papers (continued):
Sharing a sentence is not in itself a finding about the gene and the disease.
tumor (continued). "They developed an anti-disialoganglioside GD2 specific antibody-LTα fusion protein, and demonstrated that this fusion protein was able to favor subcutaneous tumor and established pulmonary metastasis eradication, and to prolong survival." (PMID 25755654, 2015). "Lymphotoxin-α (LTα) and LTβ can be expressed by T-cells and function as a mediator of tumor cell death through the LTβR." (PMID 22389673, 2012). "LTα in the TME has also been shown to promote tumor growth and metastasis." (PMID 38474119, 2024). "Moreover, the tumour volume in the LTα group was significantly less than that of the control group, whereas both the number and the proportion of infiltrated CD8+ T cells were increased." (PMID 36825382, 2023). "Lymphotoxin-α/β (LTα/β) are pro-inflammatory related cytokines of the tumor necrosis factor superfamily, and an LTα/β-driven link between immune-inflammation and cancer via changes in tumor microenvironment has been reported in BCs." (PMID 35740335, 2022). "Indeed, previous studies with a tumor-targeted antibody-LTα fusion protein showed that stimulating TNFR1 in the tumor microenvironment was able to induce MECA-79+ TA-HEV and to eradicate established tumors." (PMID 33956259, 2021). "In kidney and pancreatic tissues, the forced overexpression of LTα promotes lymphoid aggregate formation (containing T cells, B cells, and APCs) and tumor vascular reprograming, as indicated by increased expression of VCAM-1, ICAM-1, MAdCAM, and PNAd on VEC/HEV." (PMID 34054879, 2021). "In turn, the LTα expression was found to be significantly higher in HNSCCs as compared with adjacent normal tissues and may promote tumor angiogenesis by reshaping the metabolism and enhancing glycolysis in endothelial cells in a PFKFB3-dependent manner." (PMID 33917839, 2021). "Morever, in the same model, administration of a cancer-specific antigen antibody–LTα fusion protein enhanced eradication of pulmonary metastasis via an improved T-cell response evoked by LTα-dependent induction of peripheral lymphoid tissue at the tumor site." (PMID 33917839, 2021). "Lymphotoxin-alpha (LTA) is a pro-inflammatory cytokine with anti-tumor activity." (PMID 18700950, 2008). "Moreover, LTα overexpression in the tumour promoted the formation of TLSs." (PMID 36825382, 2023). "While infliximab and adalimumab are based on anti-TNF antibodies and bind only to TNF, etanercept is based on a TNFR-2-Ig fusion protein that can bind TNF and LTα, which could have consequences, since LTα potentially has a TNF-independent role in tumor control." (PMID 36358688, 2022). "Moreover, engineered LTα expression in tumour cells leads to the formation of intra-tumoral lymphoid tissue, able to sustain an efficient immune response, suggesting that signalling through LTα and its receptor plays a role in the induction of functionally competent TLS55." (PMID 35508704, 2022). "However, one cannot exclude that this cytotoxic substance contained not only LTα, but also TNF, the activity described in 1975 by Lloyd Old’s group as an endotoxin-induced serum factor that could cause tumor necrosis." (PMID 33917839, 2021). "IL-33–activated ILC2s not only coordinate with cytotoxic T cells to limit tumor growth, but also promote the formation of tertiary lymphoid structures (TLS) through lymphotoxin (LTα and LTβ) expression." (PMID 40963622, 2025). "PPI network analysis revealed these genes and modules were mainly related to tumor progression (LOXL1, IKBKE, LNX1, FOXA2, FGF17, and FGF2) and immune response (STAT4, IL23R, LTA, ITK, and IL19)." (PMID 36611170, 2023). "The five TNFSF ligand transcripts were differentially expressed by all these subsets, with tumor-infiltrating germinal cells expressing the highest levels of TNF, LTA, TNFSF10 and LTB, and tumor-infiltrating plasma cells expressing the highest levels of FASLG." (PMID 35392082, 2022).
tumor (continued). "Particularly, CD68+ macrophages have also been shown to facilitate TU-HEV formation in the Rip1Tag5 tumor model by producing the TNF receptor ligands TNFα and LTα." (PMID 34484246, 2021). "Ectopic delivery of LTα/β or LIGHT (aka TNFSF-14 or CD258) promotes PNAd+ HEV, CCL19/CCL21 production, massive naïve T cell infiltration, and (tumor-specific) cross-priming in the context of TLO structures." (PMID 24348473, 2013). "Lymphotoxin-alpha (LTA), a member of the tumor necrosis factor (TNF) family of cytokines, was initially isolated on the basis of an anti-tumor activity." (PMID 18700950, 2008). "Notably, these same malignant T cells also express LTα, whose production is induced by dysregulated JAK3/STAT5 signaling, thereby contributing to IL-6 secretion and synergizing with VEGF to support tumor vascularization." (PMID 41171472, 2025). "Theoretically, LTα, IL-6, and VEGF may promote angiogenesis, inducing an increase in endothelial cells and, thus, promoting tumor growth and spread." (PMID 34685762, 2021). "In the subsequent analysis of the potential pathways between GrB+ B cells and tumor cells, the most important incoming and outgoing L-R pairs were the signaling complexes, macrophage migration inhibitory factor (MIF) -(CD74 + CXCR4) and lymphotoxin-alpha (LTA)–(LTB + LTBR), respectively." (PMID 38386050, 2024). "In contrast, members of the TNF receptor superfamily (TNFSF), which mediate the noncanonical NF-κB pathway, a potential tumor-promoting mechanism (NCR3, CD40LG, LTA, LTB, and TNFRSF13C), were observed in East Asian and Mixed ancestry populations (TCGA)." (PMID 41387728, 2025). "Our data show that lymphotoxin alpha and not TNF derived from the tumor cells requires cIAP1 expression in the endothelium to induce tumor cell extravasation." (PMID 33546280, 2021). "Surprisingly, lymphotoxin alpha (LTA), and not TNF, secreted by the tumor cells, was critical for the extravasation." (PMID 33546280, 2021). "Mice lacking TNFR1/2 on the endothelium or LTα on CD8+ T cells have significantly decreased PNAd expression, demonstrating that LTα3 engagement of TNFR1 induces PNAd expression on the tumor vascular endothelium." (PMID 34054879, 2021). "Indeed, LTα knockout mice, which (like NOG mice) develop disorganized white splenic pulp and lack peripheral lymphoid structures, do not benefit from adoptive transfer of tumor-reactive central memory CD8+ cells, whereas WT mice do." (PMID 38184565, 2024).
cancer (66 papers, 2002 to 2025). A tumor composed of atypical neoplastic, often pleomorphic cells that invade other tissues. "It was reported that the polymorphisms of the LTA gene are closely related to cancer risk, including LAUD and other adenocarcinoma malignancies." (PMID 35879761, 2022). "Numerous studies have shown LTA polymorphisms as risk factors for cancers, but the results remain inconclusive." (PMID 24349304, 2013). "At the same time, continuous use of systemic anti-TNF/anti-LTα biologics, such as Etanercept, could result in increased risk of cancer development." (PMID 33917839, 2021). "Therefore, we conducted the current updated systematic review and meta-analysis to accurately determine the association between genetic variation of LTA gene and cancer susceptibility." (PMID 32420584, 2020). "However, since LTα-, LTβR-, and RORγt+ LTα-deficient mice all have abnormalities in the secondary lymphoid tissue formation, their susceptibility to chemically induced cancer may partially be associated with the delayed adaptive antitumor response." (PMID 33917839, 2021). "The overexpression of StAR has been shown to affect toll-like receptor 3 (TLR3), TLR6, and lymphotoxin alpha (LTα) activities, which contribute to various cancers." (PMID 35740335, 2022). "This review summarizes findings regarding the role of TNF and LTα in transplantable and chemically induced mouse cancer models and discusses some unresolved controversies." (PMID 33917839, 2021). "Here, we review the mechanisms of TNF/LTα involvement in cancer promotion and suppression as studied in mouse models." (PMID 33917839, 2021). "For LTA rs2229094 and rs746848, only four studies reported their relationship with cancer in each group." (PMID 32420584, 2020). "However, the impact of LTα–microbiota interaction on cancer progression remains largely unknown and should be addressed in the future." (PMID 33917839, 2021). "We identified multiple TNF superfamily members with direct apoptotic effects on cancer cells, including TNFSF10 (TRAIL), TNFSF14 (LIGHT), TNFSF15 (TL1A), and LTA." (PMID 40564222, 2025). "As per the QPCR array data, Rapamycin is believed to induce apoptosis in cancer cells by altering the components of the extrinsic (CD40LG, DAPK1, LTA, TNFRSF21) and intrinsic (BIRC5, BNIP3) apoptotic pathways as well as the TP73 upstream modulator." (PMID 38276004, 2024). "Lymphotoxin alpha (LTA) has a crucial role in communicating the lymphocytes with stromal cells and provoking cytotoxic effects on the cancer cells." (PMID 36929286, 2023). "The implementation of serum biomarkers such as LTα might represent an important tool in this context to stratify patients and further research on the prognostic value of these indicators of TLS formation in cancer patients should be fostered." (PMID 35508704, 2022).
infection (56 papers, 2006 to 2025). The state of being infected such as from the introduction of a foreign agent such as serum, vaccine, antigenic substance or organism. "Here, LTα levels in the V2-TTB NP group measured at week 16 + 48 hrs were negatively associated with the number of challenges required to infection (p = 0.045)." (PMID 39438480, 2024). "The intronic LTα variant 525 that affected susceptibility to infection with H. mixtum was located only 18bp from the intron-exon junction." (PMID 36693052, 2023). "Specifically, pro-inflammatory cytokines such as LTα and IFNγ drive the development of ECM during PbA infection, as mice with either LTα or IFNγ deficiency are completely resistant to ECM." (PMID 33316929, 2020). "We examined the roles of IFNγ, TNFα and LTα in brain microvessel cross-presentation during PbA infection by comparing mice deficient in each cytokine with wild type (WT) C57BL/6J mice." (PMID 26046849, 2015). "Following a low-dose aerosol infection with the highly virulent type A strain of F. tularensis, mice deficient in LTα (LTα−/−) consistently harbored approximately 10-fold fewer bacteria in their spleens at day 2 and 10-fold more bacteria in their lungs at day 4 than LTα+/+ mice." (PMID 18769490, 2008). "When challenged against an infection, these LTα knockout mice exhibited decreased cellular response and defective viral clearance." (PMID 34451529, 2021). "While the LTα level might contribute to susceptibility to acquisition, it does not appear to be through induction of mucosal-activated CD4+ T cells as targets of infection." (PMID 39438480, 2024). "However, unlike wild type mice, severe HSV-1 related morbidity such as ulceration appeared at as early as day 6 after infection in LTα–/– mice, at time point before the transition from innate to adaptive immunity." (PMID 25993659, 2015). "For instance, several studieshave shown that after infection with Mycobacterium tuberculosis, mice genetically defective in LTα (LTα−/− mice) harbour increased bacterialburdens and exhibited a shorter median time to death when compared to LTα+/+ mice." (PMID 18769490, 2008). "Importantly, LTα shares 50% homology to TNF and can signal through both TNFR1 and TNFR2, possibly compensating for TNF deficiency in KO mice during craniotomy infection." (PMID 39044282, 2024). "Phenotypes from LTα knockout mice point to a specific role of this cytokine in the development of secondary lymphoid organs, host defence against infections and inflammation, since these animals show the absence of lymph nodes and lack NK cells resulting in increased mortality against infections." (PMID 34451529, 2021). "In addition, the inflammatory responses to the infection, as reflected by the cytokine levels and leukocyte influx in the bronchoalveolar lavage fluid and histopathological analysis, were generally similar between LTα−/− and LTα+/+ mice." (PMID 18769490, 2008). "We also detected a progressive reduction in the expression of LTα, CXCL13 and its receptor, CXCR5, along the course of infection." (PMID 34804009, 2021). "In our study, reduced expression of IFNγ, LTα, ICAM-1, CXCL9 and CXCL10 were in line with impaired recruitment of CXCR3+CD8+ T cells to the brains of mice that received BCG before PbA infection." (PMID 33316929, 2020). "There are four proinflammatory cytokines: tumor necrosis factor-alpha (TNFα), lymphotoxin alpha and beta (LTA and LTB), and leukocyte specific transcript-1 (LST1) in the class III region that are important in inflammation and infection." (PMID 27812316, 2016). "Natural host ligands (i.e. BTLA and LTα) of the herpes simplex virus entry receptor, HVEM, can inhibit binding of the virus glycoprotein gD to HVEM and suppress infection." (PMID 27783670, 2016). "Unlike IFNγ, LTα was not required for brain microvessel cross-presentation during infection." (PMID 26046849, 2015).
neurological diseases (5 papers, 2022 to 2025). "During CM Plasmodium parasites sequestered in the CNS within erythrocytes cause the production of proinflammatory cytokines, such as TNF-α, LTα, IFN-γ, IL-1α, and IL-1β, which contribute to the hyperinflammatory state of this neurological disorder." (PMID 35222377, 2022).
cardiovascular diseases (4 papers, 2015 to 2025). "We also demonstrated confirmatory evidence for the causal role of four further proteins (FGF5, IL6R, LPL, LTA) in cardiovascular disease risk." (PMID 32628676, 2020).
inflammation (4 papers, 2013 to 2022). Aberrant reaction of the microcirculation characterized by movement of fluid and leukocytes from the blood into extravascular tissues. "These pathological features are reproduced in a model of chronic meningeal inflammation generated by the injection of lentiviral vectors for the lymphotoxin-α (LTα) and interferon-γ (IFNγ) genes." (PMID 33315860, 2020).
degenerative diseases (2 papers, 2021 to 2025). "First, because fundamental research on the role of cytokine LTα in disease is limited at present, the theoretical basis of the relationship between LTα and degenerative diseases, especially LTα and IVDD, is still in the initial stage of exploration." (PMID 33441130, 2021).
LTA also shares sentences with these, for which no sentence is quoted: breast carcinoma (13 papers); colorectal cancer (10); colon carcinoma (8); periodontitis (8); viral infection (8); diabetes (7); gastric cancer (7); Hypertension (7); liver fibrosis (7); osteoarthritis (6); ovarian carcinoma (6); immune diseases (5); lung carcinoma (5); Obesity (5); multiple sclerosis (4); myeloma (4); vitiligo (4); cervical cancer (3); colitis (3); coronary artery disease (3); Crohn disease (3); dry eye (3); endometriosis (3); fungal infection (3); keratoconus (3); liver disease (3); osteoporosis (3); Parkinson disease (3); psoriatic arthritis (3); uveitis (3).
A further 178 diseases each share a sentence with LTA in 2 papers or fewer.